NLRP12 (NLR family pyrin domain containing 12)
Diseases named in the same sentence as NLRP12 in open-access papers (continued):
Sharing a sentence is not in itself a finding about the gene and the disease.
melanoma (3 papers, 2023 to 2026). A malignant, usually aggressive tumor composed of atypical, neoplastic melanocytes. "To date, Z‐DNA binding protein 1 (ZBP1)‐, Absent in Melanoma (AIM)‐, receptor‐interacting serine/threonine‐protein kinase 1 (RIPK1)‐, and NLR family pyrin domain containing 12 (NLRP12)‐ PANoptosomes have been characterized at the molecular level." (PMID 41362050, 2026). "To date, four distinct PANoptosomes have been identified: Z-DNA-binding protein 1 (ZBP1), absent in melanoma 2 (AIM2), receptor-interacting protein kinase 1 (RIPK1), and nucleotide-binding leucine-rich repeat-containing receptor 12 (NLRP12) PANoptosomes." (PMID 40568592, 2025).
periodontitis (3 papers, 2020 to 2025). An acute or chronic inflammatory process that affects the tissues that surround and support the teeth. "Through RF of the identified hub genes (ACSL5, NLRP12, CCRL2, and CEACAM3), pathways that activate the immune system were implicated in PCOS and periodontitis." (PMID 38167332, 2024). "ACSL5, NLRP12, CCRL2, and CEACAM3 were identified as hub genes and diagnostic genes in both PCOS and periodontitis." (PMID 38167332, 2024). "The 4 hub genes ACSL5, NLRP12, CCRL2, and CEACAM3 may be diagnostic genes for PCOS and periodontitis." (PMID 38167332, 2024). "There is a strong expression of NLRP12 in gingival tissues with severe chronic periodontitis." (PMID 38167332, 2024). "In order to observe the different distribution of NLRP family intuitively, immunohistochemistry was applied to analyze the expression characteristics of NLRP1, NLRP2, NLRP3, NLRP6, and NLRP12 in full-thickness gingival tissue samples obtained from severe periodontitis patients and healthy people." (PMID 32903638, 2020). "Additionally, the AUCs of ACSL5, NLRP12, CCRL2, and CEACAM3 in the periodontitis training dataset were 0.771, 0.819, 0.708 and 0.785, respectively, which also suggested the diagnostic values of 4 hub genes on periodontitis were strong." (PMID 38167332, 2024). "Genes such as ACSL5, NLRP12, CCRL2, and CEACAM3 were identified as the molecular link between PCOS and periodontitis." (PMID 38167332, 2024). "Intersection of the candidate genes 1 and 2 yielded 4 hub genes (ACSL5, NLRP12, CCRL2, and CEACAM3) involved in both PCOS and periodontitis." (PMID 38167332, 2024). "However, NLRP3, NLRP6, NLRP12, and AIM2 were expressed much higher in gingival tissues with periodontitis than in healthy group, especially for NLRP3 and NLRP12." (PMID 32903638, 2020). "Moreover, NLRP12 was mostly distributed in the epithelium, while cells stained for NLRP3 were observed throughout the epithelium and lamina propria in periodontitis tissues." (PMID 32903638, 2020).
ulcerative colitis (3 papers, 2018 to 2022). An inflammatory bowel disease involving the mucosal surface of the large intestine and rectum. "As to NLRP12, patients with ulcerative colitis are associated with lower expression of NLRP12, which is the gene encoding the negative regulator of innate immune." (PMID 29416535, 2018). "The microbiome of NLRP12-deficient mice has been previously characterized as having reduced bacterial diversity and decreased abundance of the protective commensal Lachnospiraceae contributing to colonic inflammation, as in human Ulcerative Colitis patients." (PMID 35572547, 2022).
acute myeloid leukemia (2 papers, 2020). Acute myeloid leukemia (AML) is a group of neoplasms arising from precursor cells committed to the myeloid cell-line differentiation. "Recently, it has been reported that the NLRP12, through its binding to the hematopoiesis cell kinase, may impart an effect on the pathogenesis of acute myeloid leukemia." (PMID 33101293, 2020). "Bioinformatic analysis showed that HCK mRNA co-occurred with NLRP12 mRNA, but not with other NLRP mRNAs, in blood and marrow samples from acute myeloid leukemia (AML) patients." (PMID 32226298, 2020).
allergic contact dermatitis (2 papers, 2012 to 2021). An inflammatory skin condition caused by an immune response to direct contact between the skin and an allergen. "Similar to NLRP12, TLR2 has been shown to be an essential mediator of the immune response to oxazolone (OX) in an allergic contact dermatitis model." (PMID 22291998, 2012).
asthma (2 papers, 2012 to 2017). "Thus, the allergic airway inflammation models described here should be appropriate for subsequent studies that seek to decipher the contribution of NLRP12 in mediating the host response to agents associated with asthma exacerbation." (PMID 22291998, 2012). "Because contact hypersensitivity and asthma share many of the same immunopathological features, we sought to characterize the in vivo contribution of NLRP12 in common mouse models of allergic airway inflammation." (PMID 22291998, 2012). "Thus, our data shows that the acute OVA and chronic HDM models are appropriate for future studies that aim to decipher the contribution of NLRP12 in asthma exacerbations, which is an area of intense scientific and clinical interest." (PMID 22291998, 2012).
atopic dermatitis (2 papers, 2013 to 2019). "While many of the functions and activators of NLRP12 remain unknown, mutations in the NLRP12 gene have been associated with auto-inflammatory diseases such as atopic dermatitis and hereditary periodic fever syndromes." (PMID 24137163, 2013).
chronic kidney disease (2 papers, 2017 to 2023). Impairment of the renal function secondary to chronic kidney damage persisting for three or more months. "Among the NLR family members (NLRP1, NLRP2, NLRP3, NLRP6, NLRP12, and NLRC4), NLRP3 deficient mice had less tubular injury, inflammation, and renal fibrosis in chronic kidney disease (CKD)." (PMID 29100270, 2017).
CINCA syndrome (2 papers, 2013 to 2020). Chronic Infantile Neurological, Cutaneous, and Articular (CINCA) syndrome is characterized by skin rash, joint involvement, chronic meningitis with granulocytes and, in some cases, sensorineural hearing loss and ocular signs. "FCAS2 arises from pathogenic variants in NLRP12, while MWS, FCAS1, and CINCA syndrome can be attributed to gain-of-function pathogenic variants in the NLRP3 gene." (PMID 33396879, 2020).
cornea infection (2 papers, 2019 to 2021). "Prior studies found that corneal infection of NLRP3-/- mice results in more severe immunopathogenesis, and that corneal HSV-1 infection induces the NLRP3, NLRP12, and IFI16 inflammasomes." (PMID 33524073, 2021). "Since induction of inflammasomes triggers Caspase-1 activation, we next determined whether corneal infection with virulent HSV-1 strains would enhance the expression levels of one or several of the five major inflammasomes: NLRP3, NLRP6, NLRP12, IFI16/p204, and AIM2." (PMID 31367214, 2019).
gout (2 papers, 2021). A condition characterized by painful swelling of the joints, which is caused by deposition of urate crystals. "The final nine surviving monocyte-specific differentially methylated CpG sites were mapped to eight genes (PRKCZ, CIDEC, VDAC1, CPT1A, BIRC2, BRCA1, STK11, and NLRP12) that have not previously been studied in the field of gout genetics." (PMID 33493135, 2021).
hyper IgD syndrome (2 papers, 2021). "This was followed by the MVK, NLRP12, and IL36RN genes causing hyper IgD syndrome, (HIDS) and generalized pustular psoriasis (GPP) with 2 unique variants each, in 8 and 4 individuals, respectively." (PMID 34905135, 2021).
Kawasaki disease (2 papers, 2018 to 2021). A rare inflammatory disease characterized by an acute febrile, systemic, self-limiting, medium-vessel vasculitis primarily affecting children. "Up-regulation (and potentially over-activation) of NLRP12 has also been noted in patients with Kawasaki disease, a rare auto-inflammation of blood vessels in children." (PMID 33372854, 2021).
uveitis (2 papers, 2022). An inflammatory process affecting a part of or the entire uvea. "In summary, these findings uncover a novel role for Nlrp12 as a key genetic determinant of uveitis susceptibility, and the cellular mechanism by which Nlrp12 protects against uveitis could be targeted as an alternative approach for treatment of ocular autoimmunity." (PMID 35313917, 2022). "After immunization, WT mice transplanted with Nlrp12−/− BM cells developed more severe uveitis compared to control mice (WT mice transplanted with WT BM)." (PMID 35313917, 2022). "Our observations of heightened myeloid responses in Nlrp12−/− mice and a BM-cellular mechanism, further lend support to the possibility of a Nlrp12-myeloid signaling axis as a dominant mechanism in uveitis." (PMID 35313917, 2022). "Nlrp12 was dispensable for T cell priming and differentiation of peripheral Th1 or Th17 cells, and uveitis in immunodeficient mice reconstituted with either Nlrp12−/− or WT T cells was similar." (PMID 35313917, 2022). "Collectively, our data support distinct tissue-specific functions for Nlrp12 involving suppression of retinal inflammation and BM-derived macrophage responses, which together protect against perpetuation of T cell-mediated uveitis." (PMID 35313917, 2022). "Here, we examined the contribution of Nlrp12 in a T cell-mediated model of uveitis, experimental autoimmune uveitis (EAU)." (PMID 35313917, 2022). "NLRP12−/− mice developed exacerbated uveitis, which was not attributed to inherent T cell dysfunction but depended on enhanced neutrophil and macrophage accumulation, indicating that NLRP12 exerts an anti-inflammatory role to suppress uveitis." (PMID 35836195, 2022). "We show, somewhat surprisingly, that Nlrp12 exerts an anti-inflammatory role in EAU to suppress uveitis." (PMID 35313917, 2022). "Collectively, these observations support a key role for Nlrp12 in BM-derived myeloid cellular responses in mitigation of uveitis." (PMID 35313917, 2022). "We used the EAU model, which has been instrumental in defining contributions of inflammatory mediators and T cell responses to pathogenesis of uveitis, to study Nlrp12 in integration of innate and T cell-mediated responses in ocular inflammation." (PMID 35313917, 2022). "In the eye, enhanced neutrophil and macrophage accumulation could, in turn, further potentiate IRBP-reactive T cell responses and more severe uveitis in Nlrp12−/− mice." (PMID 35313917, 2022). "Compared to WT counterparts, Nlrp12−/− mice developed more severe clinical uveitis." (PMID 35313917, 2022). "Closer examination of uveitis in BM-chimeric mice revealed that Nlrp12−/− recipients transplanted with WT BM still developed significantly worse uveitis compared to WT controls (WT mice transplanted with WT BM), thereby supporting a secondary, non-hematopoietic cellular role for Nlrp12." (PMID 35313917, 2022). "Uveitis was evaluated by clinical and histopathological scoring, and comparisons were made in WT vs. Nlrp12−/− mice, lymphopenic Rag1−/− mice reconstituted with WT vs. Nlrp12−/− CD4+ T cells, or among bone marrow (BM) chimeric mice." (PMID 35313917, 2022). "Therefore, in consideration of potential mechanisms by which Nlrp12 expression is connected to myeloid-derived responses, we examined uveitis in BM-chimeric mice." (PMID 35313917, 2022). "Based on our observation that CD4+ T cells were expanded within uveitic eyes of Nlrp12−/− vs. WT mice, we evaluated whether Nlrp12 might inherently control T cells in mitigating uveitis." (PMID 35313917, 2022). "Together, these data reveal a somewhat unanticipated protective role for Nlrp12 in uveitis." (PMID 35313917, 2022). "Third, given several differences of cytokine/chemokine transcript regulation (e.g. of Cxcl1 and Cxcl10) using RT-qPCR, it would be of interest to confirm these findings at the protein level, as well as future mechanistic studies to explore Nlrp12-mediated protection against uveitis." (PMID 35313917, 2022).
uveitis (continued). "Similarly, Nlrp12−/− mice transplanted with WT BM cells developed less severe uveitis compared to those transplanted with Nlrp12−/− BM." (PMID 35313917, 2022). "Reconstituted Rag1−/− recipients were immunized with IRBP1–20 and the ability of Nlrp12−/− vs. WT CD4+ T cells to expand and trigger uveitis was evaluated." (PMID 35313917, 2022). "The exacerbated uveitis observed in Nlrp12−/− mice was not attributed to inherent T cell dysfunction, but was due rather, to multi-cellular mechanisms involving BM-derived myeloid cellular responses as well as non-hematopoietic cell contributions." (PMID 35313917, 2022). "Moreover, the severity of uveitis was not significantly different, indicating that the mechanism by which Nlrp12 suppresses EAU is not T cell-intrinsic." (PMID 35313917, 2022).
Yersinia infection (2 papers, 2012 to 2025). "NLRP12 was also recently found to induce inflammasome activation in response to Y. pestis infection, and both NLRP3 and NLRP12 contributed to host defense against Yersinia infection, presumably via induction of caspase-1-dependent IL-1β and IL-18." (PMID 23226685, 2012).
acute promyelocytic leukemia (1 paper, 2024). An aggressive form of acute myeloid leukemia (AML), characterized by arrest of leukocyte differentiation at the promyelocyte stage, due to a specific chromosomal translocation t(15;17) in myeloid cells. "We also investigated expression of human NLRP12 using the HL-60 cell line derived from human acute promyelocytic leukemia." (PMID 39076995, 2024).
adult-onset Still disease (1 paper, 2022). A rare inflammatory multisystem disorder characterized clinically by fever of unknown origin, arthralgia or arthritis, hyperleucocytosis, and typical skin rash. "Another 2017 paper showed that PBMCs taken from individuals with adult-onset Still’s disease (AOSD; an autoinflammatory condition), when compared to healthy controls, displayed elevated levels of NLRP3 mRNA and decreased expression of NLRP7, NLRP2, and NLRP12." (PMID 36298668, 2022).
Ataxia (1 paper, 2019). Ataxia refers to impaired coordination of voluntary muscle movement. "NLRP12 also suppresses NFκB activation, and the lack of Nlrp12 results in atypical EAE, with ataxia and balance deficits." (PMID 31781124, 2019).
bacterial pneumonia (1 paper, 2013). Acute infection of the lung parenchyma caused by bacteria (e.g., Streptococcus pneumoniae, Haemophilus influenzae, Chlamydia pneumoniae, Mycoplasma pneumoniae, and Legionella pneumophila). "Together, the previous in vitro findings and the in vivo data associated with the innate immune response suggested that the Nlrp12−/− mice would serve as an appropriate model to evaluate disease pathogenesis during bacterial pneumonia and Mtb infection." (PMID 23577168, 2013). "Here, we assessed the role of NLRP12 in acute and chronic models of bacterial pneumonia and Mtb infection." (PMID 23577168, 2013).
Chronic colitis (1 paper, 2023). A chronic inflammatory disease of the large intestine (colon, cecum and rectum). "However, the data of this study imply that NLRP12 downregulates NF-κB and MAPK pathways in the colon during acute colitis, but not chronic colitis or tumorigenesis." (PMID 37581937, 2023).
Cirrhosis (1 paper, 2019). A chronic disorder of the liver in which liver tissue becomes scarred and is partially replaced by regenerative nodules and fibrotic tissue resulting in loss of liver function. "Considering the critical role of gut microbiota and TLR pathways in inflammatory liver disorders, future studies should investigate the role of NLRP12 in liver fibrosis, cirrhosis, and non-alcoholic fatty liver syndrome using appropriate animal models." (PMID 30990169, 2019).
colorectal adenocarcinoma (1 paper, 2023). The most common type of colorectal carcinoma. "To understand the relevance of the observed connection between NLRP12 and β-catenin in human CRC, we measured the expression of NLRP12, β-catenin, and p-GSK3β in human colorectal adenocarcinoma and adjacent nontumor tissue." (PMID 37581937, 2023).
DNA repair deficiency (1 paper, 2021). "In a newly published paper, the researchers further investigated the essential role of NLRP12 in HSC maintenance and found that persistent DNA damage-induced NLRP12 improves HSC function in both mouse and human models of DNA repair deficiency (Fanca−/− mice)." (PMID 33435298, 2021).
dry eye (1 paper, 2023). "NLRP12/NLRC4 knockdown, GSDMD knockout, or the neutralization of mature IL-33 can obviously attenuate the damage to corneal epithelial cells, indicating that these molecules could be key targets for dry eye treatment in the future." (PMID 37250902, 2023).
dysplasia (1 paper, 2023). A usually neoplastic transformation of the cell, associated with altered architectural tissue patterns. "We previously demonstrated that Nlrp12-deficient mice are susceptible to chemical carcinogen–induced colorectal tumorigenesis, with a higher incidence of high-grade dysplasia and invasive adenocarcinoma." (PMID 37581937, 2023).
endotoxemia (1 paper, 2018). "Thus, NLRP12 is dispensable for protecting mice against endotoxemia, but rather function as a negative regulator of NOD2 signaling in mice." (PMID 30559449, 2018).
Flavivirus Infections (1 paper, 2021). Infections with viruses of the genus FLAVIVIRUS, family FLAVIVIRIDAE. "In summary, this finding sheds light on the mechanism of NLRP12 in inhibiting viral replication, which provided a potential target for therapeutic strategies aimed at controlling flavivirus infection especially DENV infection." (PMID 34956178, 2021).